TREX1 (three prime repair exonuclease 1)
Diseases named in the same sentence as TREX1 in open-access papers (continued):
Sharing a sentence is not in itself a finding about the gene and the disease.
tumor (continued). "Thus, Trex1 is an upstream regulator of radiation-driven anti-tumour immunity." (PMID 28598415, 2017). "Based on the critical role of TREX1 for determining sensitivity to radiotherapy, it will be interesting to analyse how SPP expression in tumours impacts on TREX1 function either by increasing its turnover or by increasing its mobility in the cell." (PMID 40072623, 2025). "After the mice were killed, the expression of TREX1, IFN-β, PD-L1, and CD8+T cell infiltration in tumor tissue was found in order to investigate the effects of carbon ion or X-ray coupled PD-1 inhibitor on the immune milieu of cancers in vivo." (PMID 38495488, 2024). "TREX1 counteracts potential cGAS-STING induction in the TME and thereby the anti-tumor immune response by degrading tumor-derived DNA that is either spontaneously generated or induced by DNA damaging therapeutic approaches." (PMID 38022587, 2023). "In contrast, radiation given in fractionated doses below the dose threshold for Trex1 induction stimulates dying tumor cells to release IFN-β cytokine, which recruits Batf3-dependent DCs and activates anti-tumor CD8+ T cells." (PMID 36993986, 2023). "TREX1 is the gatekeeper enzyme of the cGAS-STING pathway, and tumor-derived DNA generated spontaneously or induced by radiotherapy or chemotherapy can be degraded by TREX1." (PMID 33868310, 2021). "In several tumor categories, methylation of TMEM173 (STING), TREX1, and C6orf150 (cGAS) was correlated with GMD expression." (PMID 33676569, 2021). "In contrast, a single fraction of 20 Gy RT increased the expression of TREX1 within tumor cells, preventing STING activation and its ability to augment the systemic anti-tumor activity of ICB therapy." (PMID 35095911, 2021). "Further, western blot and RT-qPCR experiments were used to determine the expression of TREX1 and mRNA in A375, SK-HEP-1, SK-MEL-1, and MV3 tumor and the HPM normal cells." (PMID 34519260, 2021). "In contrast, when radiation is given in multiple, low-dose fractions, Trex1 induction is prohibited, and it stimulates cancer cells to produce IFN and mediate tumor regression." (PMID 33142765, 2020). "Furthermore, heatmap analysis revealed that TREX1 and RRM2 expression levels were significantly higher in tumor tissues compared to normal tissues, whereas GPX2, DUOX1, and DUOX2 were expressed at lower levels in tumor tissues." (PMID 41346575, 2025). "TREX1 has a protumorigenic effect by inhibiting the cGAS-STING-mediated immune activation within and outside the tumor and by limiting checkpoint activation of the adaptive immune response in the tumor microenvironment." (PMID 40581636, 2025). "This suggests that generation of cytosolic DNA through pharmacological TREX1 inhibition, could be used in conjunction with ICB therapy to enhance overall tumor immunogenicity." (PMID 39178223, 2024). "Furthermore, CRISPR-mediated deletion of TREX1 in RPP-A-EtopR cells induced the expression of ISGs in a STING-dependent manner, suggesting a tumor-intrinsic innate immune response." (PMID 39177280, 2024). "Later on, the same group has shown that repeated medium-high doses, below a threshold of 10-12 Gy, do not induce DNA exonuclease Trex1, and thus elevates interferon-β production in tumor cells, which promotes recruitment and activation of Batf3-dependent DCs." (PMID 34177901, 2021). "Indeed, at doses higher than 12 Gy, cytosolic dsDNA is cleared by three prime repair exonuclease 1 (TREX1), precluding the activation of the cGAS pathway to induce type I interferon, and abolishing the radiotherapy-induced anti-tumor immune response." (PMID 34386508, 2021). "Similarly, our findings indicated reduced TREX1 expressions in human melanoma cancer as was expressed in A375, SK-HEP-1, SK-MEL-1, and MV3 tumor cell lines." (PMID 34519260, 2021).
tumor (continued). "Indeed, TREX1 is an upstream regulator of radiation-driven anti-tumor immunity and STING is essential to promote tumor rejection in immunocompetent mice treated with the anticancer agent Topotecan." (PMID 34249949, 2021). "If Trex1 is not induced, it leads to the priming of tumor-specific CD8+ T cells that, in the presence of immune checkpoint inhibitors, mediate complete durable regression of irradiated and non-irradiated tumors." (PMID 33142765, 2020). "Thus, the balance between levels of dsDNA and Trex1 dictates IFN-stimulatory DNA accumulation in the cytoplasm of irradiated cells, and the subsequent development of anti-tumour T cell responses." (PMID 28598415, 2017). "Finally, we examined TREX1 and FANCF levels in the tumour ECs from a xenograft GBM model and found significant downregulation of both at the RNA level." (PMID 27886180, 2016). "Our data suggests that radiation induced miR-103 downregulates TREX1 in ECs, decreases angiogenesis and leads to the secretion of proinflammatory mediators that may upregulate Fas and TRAIL pathways in tumour cells." (PMID 27886180, 2016). "Thus, it is not surprising that tumor cells induce TREX1 upon CIN in a cGAS/STING-dependent manner as an adaptive feedback mechanism to promote removal of cytosolic DNA, and thus, allow for immune evasion." (PMID 40098954, 2025). "Reactivate STING-interferon (IFN) signaling to restore anti-tumor immunity;Re-release STING-IFN signals to recruit T cells and natural killer (NK), cells that are sensitive to NK cell-derived IFN γ;The combination of TREX1 inhibitor and PD-1 can enhance immunogenicity." (PMID 40568576, 2025). "Therefore, we then assessed whether the tumor-intrinsic immune signaling, including increased MHC-I antigen presentation, induced in RPP-A-EtopR cells following TREX1 deletion can lead to T cell activation in vitro." (PMID 39177280, 2024). "In tumors treated with irradiation doses exceeding the Trex1 induction threshold, clearance of dsDNA from cancer cell sol hinders IFN-β release in cancer cells, resulting in a reduced recruitment of DCs and insufficient activation of CD + 8 T cells leading to diminished local tumor regression." (PMID 37667279, 2023). "Repeated radiations at doses (8 Gyx3) above the threshold of Trex1 induction greatly amplified type-1 IFN production, resulting in recruitment and activation of Batf3-dependent dendritic cells, which are essential for priming of CD8+ T cells that induce tumor rejection in the context of ICI." (PMID 36077606, 2022). "Thus like Trex1, ADAR inactivates the stimuli at the origin of the IFN I production by tumor cells." (PMID 34249754, 2021). "However, our data unequivocally demonstrate that the abscopal effect is abrogated when cancer cells in the irradiated tumour do not express cGAS/STING or overexpress Trex1, which preclude cancer cell-intrinsic activation of IFN-I pathway." (PMID 28598415, 2017). "Therefore, the low expression of TREX1 gene may reduce the cytotoxicity of CTL and NK on tumor cells, so that the tumor cells occur to immune escape and the tumor growth can be promoted." (PMID 27881153, 2016). "The DNA three-prime repair exonuclease Trex1 (TREX1) is estimated to have a diminishing effect on immunogenicity by degrading accumulated DNA in the cytosol; this could activate the cGAS-STING pathway, which essential for CD8+ T cells that mediate systemic tumor rejection in the context of ICI." (PMID 36612206, 2022). "In contrast, hypofractionated RT (8 Gy/day on three consecutive days) did not induce Trex1 and, therefore, promoted stronger cGAS-STING activity as well as higher expression of IFN-β in tumor cells." (PMID 34830176, 2021). "Conversely, when TREX1 is not induced, the cGAS-STING pathway is activated and recruits BATF3-dependent dendritic cells that activate anti-cancer CD8+ T cells to mediate systemic tumor immunity." (PMID 39759116, 2025).
tumor (continued). "Radiotherapy leads to dsDNA accumulation in cancer cells when Trex1 is not activated type I IFNs are activated through the cGAS/STING pathway, downstream recruitment of DCs, and activation of CD + 8 T cells or anti-PD-1 antibodies to initiate tumor rejection." (PMID 37667279, 2023). "In agreement with the major role of TREX1 as an anti-inflammatory player, Trex1 knockout mice and TREX1D18N exonuclease defective mice develop an inflammatory systemic phenotype, but they are not tumour prone." (PMID 35883600, 2022). "Interestingly, multiple smaller fractions of radiation (8 Gy*3) did not induce higher levels of Trex1, rather it induced more IFN-β production and activation of Batf3-dependent DCs, leading to enhanced anti-tumor T cells responses." (PMID 30692991, 2018).
cancer (47 papers, 2012 to 2025). A tumor composed of atypical neoplastic, often pleomorphic cells that invade other tissues. "Out of 16 cancer-associated TREX1 variants, 6 (37.5%) were predicted to be pathogenic by AlphaMissense (G23D, G23V, P29S, L44P, L87P, and W210R)." (PMID 40581636, 2025). "We compared the impact of TREX1 variants predicted by our modeling to available predictions from two popular protein structure resources, proteome-wide AlphaMissense and cancer-centered COSMIC-3D." (PMID 40581636, 2025). "In this context, it is of note that the E3 ubiquitin ligase TRIM24 has been implicated in cancer cells to initiate TREX1 degradation by the proteasome." (PMID 40072623, 2025). "In contrast, knowledge about the potential significance of TREX1 variants in cancer is very limited." (PMID 40581636, 2025). "Germline pathogenic TREX1 mutations are known to lead to hereditary autoimmune and autoinflammatory disorders, whereas the consequences of TREX1 mutations in cancer remain poorly understood." (PMID 40581636, 2025). "We developed a catalog of germline and somatic TREX1 variants in human disease samples, cancer cell lines and organoids, and population-based samples." (PMID 40581636, 2025). "Even though an increasing number of studies have highlighted the importance of TREX1 as a novel target for cancer treatment, understanding of consequences of somatic or germline TREX1 variants remains limited." (PMID 40581636, 2025). "Functional impact of human cancer-associated TREX1 protein sequence variants was predicted using different approaches with consistent results." (PMID 40581636, 2025). "Our results support a cancer model whereby TREX1 upregulation is associated with chemotherapy resistance, as well as resistance to chemoimmunotherapy or ICB therapies by suppressing cGAS-STING-dependent innate immune response." (PMID 39177280, 2024). "Cancer cells utilize this mechanism of TREX1 action to inhibit the activation of cGAS-STING caused by DNA damage and thus realize immune escape." (PMID 38495488, 2024). "Accordingly, TREX1 activity was shown to be negatively correlated with outcomes in multiple cancers and its upregulation is associated with cancer cell treatment, in particular radiotherapy." (PMID 38022587, 2023). "The association between TREX1 and cancer has been reported, with research concluding that TREX1 targeting is a possible novel approach for cancer therapy." (PMID 34519260, 2021). "TREX1 has been associated with cancer cell sensitivity to DNA-damaging agents and with DNA repair or DNA degradation in apoptotic cells after drug exposure." (PMID 32586373, 2020). "RT-induced abscopal responses with PD-1 blockade were additionally shown to be regulated by Trex1 where induction of Trex1 expression in cancer cells resulted in loss of abscopal responses in mice treated with the combination." (PMID 29866197, 2018). "Loss of one or both copies of TREX1 frequently involved a broader deletion containing the chromosomal region surrounding TREX1 or the entire short arm of chromosome 3, which are common in many cancer types." (PMID 40581636, 2025). "It is possible that recessive TREX1 variants may be present in the germline of some cancer patients or emerge as de novo somatic mutations in tumors." (PMID 40581636, 2025). "Furthermore, deletion or inactivating mutations in the C-terminal region of TREX1 in chromosomally unstable cancer cells disrupted micronuclear DNA degradation and increased cGAS activation." (PMID 40581636, 2025). "Our findings provide novel insight into the role of TREX1 molecular variation in cancer, where genetic or epigenetic loss of TREX1 activity may improve susceptibility to treatment." (PMID 40581636, 2025). "Based on the extent of the loss of TREX1 function, some of these therapeutic vulnerabilities may be more prevalent in specific cancer categories." (PMID 40581636, 2025).
cancer (continued). "Interestingly, cancer cells exhibit cytoplasmic accumulation of DNA, which is associated with the limited activity of TREX1 induced by various mechanisms in cancers." (PMID 38877472, 2024). "Additionally, TREX1 degradation of tumor-derived DNA has been implicated in limiting antitumor immunity and cancer immunotherapies." (PMID 35879334, 2022). "In addition, treatment of cancerous cells in vitro with UV-light or various genotoxic anti-cancer drugs is associated with TREX1 upregulation, and siRNA knockdown of TREX1 enhances cancer cell death following these treatments." (PMID 33868310, 2021). "Chronic low-level DNA damage and enhanced sensitivity to genotoxic stress also suggest that patients with TREX1 mutations may have an increased cancer risk, like patients with SAMHD1 mutations." (PMID 27230542, 2016). "However, TREX1 gene deletion in tumors was associated with unfavorable patient outcomes, most likely due its frequent co-occurrence with the loss of the entire 3p chromosomal arm, which contains known cancer-related genes." (PMID 40581636, 2025). "However, it is possible that TREX1 mutations in patients with cancer may instead increase immune activation in cancer cell along with STING stimulation." (PMID 34335558, 2021). "Recent evidence indicates that TREX1 plays a significant role in cancer progression and immune evasion." (PMID 41346575, 2025). "The broader 3p21 chromosomal region containing TREX1 is frequently deleted in cancer, however, most attention has been drawn to the nearby 3p21.3 and 3p21.1 regions, which contain important tumor suppressor genes." (PMID 40581636, 2025). "The prognostic signature we have constructed includes TREX1, NOX4, and RRM2, with the latter two also being closely associated with cancer progression." (PMID 41346575, 2025). "Recent studies provided new insight into the protumorigenic role of TREX1, its effects on increased cancer resistance to treatment, and suggested TREX1 as an important anticancer drug target." (PMID 40581636, 2025). "At higher radiation doses (12 Gy and 18 Gy), TREX1 is sufficient to scavenge cytoplasmic dsDNA accumulated in some cancer cells, thus preventing excessive activation of the cGAS-STING pathway and inhibiting the downstream interferon (IFN-I) responses." (PMID 39736508, 2024). "Collectively, these results emphasize that details of the radiation treatment (e.g., dose and fractionation) as well as the cancer cells (e.g., autophagy, TREX1 activation) are important considerations for evaluating radiation-induced immunogenic responses." (PMID 38659582, 2024). "Here, we provide the first evidence that expression of TREX1 is highly induced in drug-resistant SCLC cells compared with untreated naive cancer cells." (PMID 39177280, 2024). "Research is ongoing to explore the potential of targeting TREX1 in cancer treatment, aiming to counteract its immunosuppressive effects and improve the efficacy of cancer immunotherapies." (PMID 38881902, 2024). "To investigate the association between TREX1 and chemoresistance in SCLC further, we next evaluated TREX1 mRNA expression levels across human SCLC cell lines with available drug-response data from the Cancer Cell Line Encyclopedia." (PMID 39177280, 2024). "Micronuclear DNA or chromatin bridges were shown to trigger an IFN response in cancer cells treated with genotoxic drugs, and TREX1 was reported to limit cGAS activation in genetically unstable cells by degradation of micronuclear DNA." (PMID 35634291, 2022). "They further found that 20 Gy and 30 Gy single dose can attenuate cellular immunogenicity by inducing the DNA exonuclease Trex1 in various cancer cells, thereby degrading cytoplasmic DNA in irradiated cells." (PMID 36713375, 2022). "Studies indicating TREX1 expression is induced by genotoxic stress and that TREX1 exonuclease activity protects cancer cells from anticancer drugs and radiation suggest TREX1 inhibition would promote anti-cancer effects." (PMID 33868310, 2021).